EGFR (epidermal growth factor receptor)
Diseases named in the same sentence as EGFR in open-access papers (continued):
Sharing a sentence is not in itself a finding about the gene and the disease.
non-small cell lung carcinoma (continued). "Osimertinib is a standard treatment for patients with EGFR-mutated non-small cell lung carcinoma (NSCLC)." (PMID 37760942, 2023). "In a recent study, it has been demonstrated that tyrosine kinase inhibitor (TKI) resistance in non-small cell lung cancer (NSCLC) could be caused by mutated epidermal growth factor receptor (EGFR) which uses the regulation of the fatty acid synthase (FASN) to induce TKI." (PMID 37328876, 2023). "Besides, ESM1 mediated the progression of non-small cell lung cancer with EGFR mutation." (PMID 37476182, 2023). "Further studies revealed the EGFR T790M mutation in treatment-naive non-small cell lung carcinoma (NSCLC) and as a rare germline mutation strongly associated with NSCLC." (PMID 37265791, 2023). "It remains uncertain whether first-line treatment with upfront brain radiotherapy (RT) in combined with epidermal growth factor receptor tyrosine kinase inhibitors (EGFR-TKIs) is superior to EGFR-TKIs alone for EGFR-mutated non-small cell lung cancer with newly diagnosed brain metastases (BMs)." (PMID 37904083, 2023). "Mutations identified in the EGF receptor (EGFR) represent tumour-specific biomarkers for non-small cell lung carcinoma (NSCLC)." (PMID 36144183, 2022). "A high expression of EGFR was associated with increased gene copy numbers, and non-small cell lung cancer patients given gefitinib were associated with significantly improved responses, lower progression rates and improved survival compared with tumors with low EGFR expression." (PMID 36291859, 2022). "However, some studies revealed that patients diagnosed with EGFR-mutated non-small-cell lung cancer could draw limited benefit from immunotherapy." (PMID 36267410, 2022). "In the case of epidermal growth factor receptor (EGFR) mutation-positive non-small-cell lung cancer (NSCLC), age-related factors might be less influential because the first-line treatment generally comprises a monotherapy with EGFR tyrosine kinase inhibitors (TKIs)." (PMID 36422186, 2022). "In patients with non-small cell lung carcinoma (NSCLC) who had EGFR T790M mutations that are resistant to both first- and second-generation EGFR-TKIs, it can help achieve a median progression-free survival (PFS) of approximately 10 months." (PMID 34026823, 2021). "Besides the T790 M mutation, it may coexist with bypass pathway activation in real clinical cases for patients with EGFR mutations who resisted to the first- and second-generation tyrosine kinase inhibitors (TKIs) in non-small cell lung cancer (NSCLC)." (PMID 34397683, 2021). "Despite the huge amount of oncologic research involved in liquid biopsy, the US FDA approved only in 2016 the first liquid biopsy test for analysis of EGFR mutations in Non-Small Cell Lung Carcinoma (NSCLC) patients." (PMID 34073560, 2021). "Though patients with sensitizing epidermal growth factor receptor (EGFR) mutated non-small cell lung cancer have been known to have rapid and durable responses to tyrosine kinase inhibitors, a subset of patients have inferior outcomes and may benefit from therapy escalation." (PMID 33804721, 2021). "While accumulating evidence has shown that the malfunctions of EGFR caused by activating mutations initiate constitutive engagement and activation of downstream effector signaling, which account for approximately 10~30% oncogenesis of non-small cell lung cancer (NSCLC)." (PMID 34070173, 2021). "The use of epidermal growth factor receptor tyrosine kinase inhibitors (EGFR-TKIs) has been approved as a treatment for advanced non-small cell lung carcinoma (NSCLC) with EGFR-activating mutations." (PMID 34596125, 2021). "Non-small-cell lung cancer (NSCLC) is the most common type with 40% of the patients presenting with adenocarcinoma Approximately 10–20% of Caucasian patients with non-resectable lung adenocarcinoma have somatic mutations of the epidermal growth factor receptor (EGFR) gene." (PMID 32328874, 2020).
non-small cell lung carcinoma (continued). "Upregulation or mutation of EGFR has been associated with the progression of non-small cell lung carcinoma (NSCLC), pancreatic cancers, colorectal cancers, and glioblastomas, among other tumors." (PMID 32974013, 2020). "Mutations identified in the epidermal growth factor receptor (EGFR) predict sensitivity to EGFR-targeted therapy for non-small cell lung carcinoma (NSCLC)." (PMID 32722209, 2020). "A clinical study found that survivin mRNA levels in blood were strongly associated with a poor response to EGFR-TKI treatment in patients with non-small cell lung cancers, indicating that survivin expression may be a predictor of intrinsic resistance to EGFR-TKIs." (PMID 30729097, 2019). "Furthermore, there may be benefit with combining MIs with iEGFRs in other cancers where iEGFRs are currently clinically approved and utilized in treatment, such as in non-small cell lung cancer with activating EGFR mutations." (PMID 31763368, 2019). "As an example, one study in non-small lung cell cancers showed that drug-resistant tumor cells with acquired resistance conferred by the EGFRT790M mutation could be re-sensitized to EGFR TKIs by co-targeting them with navitoclax, an inhibitor of BCL-2 and BCL-XL." (PMID 31921698, 2019). "Genetic alterations within tumors may influence immune system engagement eventually also impacting therapy response; in non-small cell lung cancer (NSCLC) cell lines EGFR mutations or EML4-ALK fusions activate the PD-1/PD-L1 pathway via PD-L1 upregulation, inducing immune escape." (PMID 30670970, 2018). "EGFR is one of the most frequently mutated “driver” genes in non-small cell lung carcinoma (NSCLC) and EGFR-TKIs are used for the treatment of EGFR-mutated-NSCLC." (PMID 29540837, 2018). "Epidermal growth factor receptor (EGFR) T790M mutation is the most frequent mechanism which accounts for about 60% of acquired resistance to first-generation EGFR tyrosine kinase inhibitors (TKIs) in non-small cell lung cancer (NSCLC) patients harboring EGFR activating mutations." (PMID 29163853, 2017). "However, recent studies investigating the secondary EGFR T790M resistance mutation in advanced non-small cell lung cancer (NSCLC) patients showed that about 20-30% of tissue T790M mutations were not detectable in plasma-ctDNA, even with highly sensitive digital PCR technologies." (PMID 29156792, 2017). "Therefore, in non-small cell lung cancer and colorectal cancer it is important also as a therapeutic target, where in case of mutation either tyrosine kinase inhibitors or monoclonal antibodies against EGFR are used in routine practice." (PMID 28377929, 2017). "In non-small cell lung cancer several different mutations in the EGFR tyrosine kinase domain confer sensitivity to receptor tyrosine kinase inhibitors, but the tumourigenic potential of EGFR mutations in breast cells and their potential for targeted therapy is unknown." (PMID 25969993, 2015). "Afatinib has anti-tumor effect in non-small cell lung carcinoma (NSCLC) with epidermal growth factor receptor (EGFR) mutation." (PMID 25537503, 2015). "EGFR-targeted drugs could be used to treat patients with glioblastomas that exhibit these characteristics in a similar fashion to some non-small-cell lung carcinomas that contain activating EGFR mutations and that show significant responses to the EGFR inhibitors erlotinib and gefitinib." (PMID 25908947, 2015). "EGFR overexpression has been observed in 40% to 80% of non-small cell lung carcinoma (NSCLC) cases and multiple mutations for the EGFR receptor have been described and linked with malignancy." (PMID 24638075, 2014). "EGFR is overexpressed in more than 60% of non-small cell lung carcinomas (NSCLC) and activating mutations have been detected in approximately 20% of all NSCLC patients." (PMID 25594026, 2014).
non-small cell lung carcinoma (continued). "Similarly, EGFR gene copy number has also been evaluated as a potential predictor of response of tyrosine kinase inhibitors (TKIs) in non-small-cell lung cancer patients, and a meta analysis has demonstrated an association between increased EGFR copy number, and improved survival outcomes." (PMID 23441167, 2013). "EGFR inhibitors such as gefitinib have proven successful in the treatment of certain cancers, particularly non-small cell lung cancers (NSCLCs) harboring activating mutations within the EGFR gene, but the molecular mechanisms leading to tumor regression remain unknown." (PMID 17973573, 2007). "These agents are seeing increasing clinical adoption, with European Medicines Agency approvals in haematological malignancies and selected solid tumours such as uveal melanoma and EGFR-mutant non-small-cell lung cancer." (PMID 42099877, 2026). "In-depth analysis of these genes revealed enrichment in several KEGG pathways, including Cellular Senescence, Pathways in Cancer, Non-small Cell Lung Cancer, EGFR Tyrosine Kinase Inhibitor Resistance, and the MAPK signaling pathway." (PMID 41490177, 2026). "ROS1 rearrangement is a rare mechanism of acquired resistance to epidermal growth factor receptor tyrosine kinase inhibitors (EGFR-TKIs), with an incidence of less than 1% in non-small cell lung cancer (NSCLC)." (PMID 41668738, 2026). "In the last two years, exciting advances have been made in the treatment of epidermal growth factor receptor (EGFR)-mutant advanced non-small-cell lung cancer (NSCLC)." (PMID 41590374, 2026). "SMARCA4-deficient non-small cell lung cancer (SMARCA4-dNSCLC) is an aggressive malignancy with poor prognosis, rarely harboring EGFR, ALK, or ROS1 alterations." (PMID 41684594, 2026). "EGFR alterations are found in approximately 40–80 % of non-small cell lung cancers (NSCLC), especially adenocarcinomas and Asian populations." (PMID 41560835, 2026). "These ROS play a role in cell signaling and can influence tumor progression and resistance to therapies, particularly in cancers like non-small-cell lung cancer (NSCLC), where they are linked to EGFR-TKI resistance." (PMID 41562694, 2026). "Rationale: Epidermal growth factor receptor tyrosine kinase inhibitors (EGFR-TKIs) are a standard therapy for non-small cell lung cancer (NSCLC)." (PMID 41695485, 2026). "The EGFR signaling pathway is a critical driver in the occurrence and development of non-small cell lung cancer (NSCLC)." (PMID 41971100, 2026). "EGFR-TKIs are recommended as the standard first-line therapy for non-small-cell lung cancer (NSCLC)." (PMID 41301709, 2025). "In human non-small cell lung cancer, particularly epidermal growth factor receptor (EGFR)-mutant subtypes, PD-1/PD-L1 inhibitors show limited efficacy." (PMID 41230456, 2025). "Although targeted therapy has significantly improved the prognosis of patients with advanced non-small cell lung cancer (NSCLC), the treatment of patients with rare EGFR compound mutations remains a challenge." (PMID 40963567, 2025). "The epidermal growth factor receptor (EGFR) signaling pathway is active in non-small cell lung cancer (NSCLC)." (PMID 41430724, 2025). "Non-small-cell lung cancer (NSCLC) is a leading cause of cancer-related deaths worldwide, with epidermal growth factor receptor (EGFR) mutations present in a substantial proportion of patients." (PMID 39941826, 2025). "Abnormalities in the epidermal growth factor receptor (EGFR), such as gene amplification and mutations leading to constant activation, are common in non-small cell lung cancer (NSCLC)." (PMID 40168312, 2025). "Oncogenic driver mutations, particularly EGFR and ALK, are known to increase the risk of brain metastases in non-small cell lung cancer (NSCLC) patients." (PMID 40496607, 2025). "Amivantamab (EGFR×MET), approved for non-small-cell lung cancer (NSCLC) with EGFR exon 20 insertions, combines dual receptor blockade with Fc-mediated cytotoxicity." (PMID 41262250, 2025).
non-small cell lung carcinoma (continued). "Using the large-scale clinico-genomic database LC-SCRUM-Asia, 189 patients with non-small cell lung cancer harboring EGFR Exon20 in-frame insertions were identified." (PMID 40076686, 2025). "MAP17 has also been shown to induce resistance to certain treatments, such as EGFR and tyrosine kinase inhibitors, in some tumors like non-small-cell lung cancer." (PMID 40805270, 2025). "Mairei overcomes resistance to osimertinib in EGFR-mutant non-small-cell lung cancer by suppressing ERK1/2-related cholesterol biosynthesis." (PMID 40867897, 2025). "For example, it inhibits the growth and invasion of gemcitabine-resistant non-small-cell lung cancer (GR-NSCLC) cells by inducing the lysosomal degradation of the EGF receptor (EGFR) and downregulating the CIP2A/PP2A/Akt signaling axis." (PMID 40869325, 2025). "EGFR TKIs, including dacomitinib and afatinib, are key drugs used to treat Non-Small Cell Lung Cancer (NSCLC)." (PMID 41304759, 2025). "EGFR is involved in various cancers, including breast cancer, head and neck squamous cell carcinoma, colon cancer, ovarian cancer, pancreatic cancer, non-small-cell lung cancer (NSCLC), melanoma, and thyroid cancer." (PMID 40943615, 2025). "Patients with PD-L1-negative, EGFR/ALK wild-type metastatic non-small cell lung cancer (NSCLC) exhibit limited responses to immune checkpoint inhibitors (ICIs)." (PMID 40625736, 2025). "EGFR overactivation due to aberrant signaling can lead to various cancers, including non-small cell lung cancer (NSCLC)." (PMID 40194950, 2025). "Erlotinib is a reversible, small molecule ATP-competitive EGFR inhibitor that is primarily used in the treatment of non-small cell lung cancer." (PMID 40496561, 2025). "This study investigates the expression and immunosuppressive role of IL-35 in epidermal growth factor receptor (EGFR)-mutant non-small cell lung carcinoma (NSCLC), with a focus on its interaction with natural killer (NK) cells." (PMID 41357575, 2025). "Although the third-generation EGFR-TKIs can conquer resistance caused by the T790M mutation and are now the first-line standard for treating EGFR-mutant NSCLC (non-small cell lung cancer), acquired resistance remains a challenge." (PMID 40872626, 2025). "In non-small cell lung cancer, for instance, EGFR-mutant tumors with MET amplification, HER2 mutations, or PIK3CA alterations frequently develop resistance to EGFR inhibitors." (PMID 40076838, 2025). "For patients suffering from non-small cell lung cancer, despite the fact that EGFR–tyrosine kinase inhibitors (EGFR-TKI) can be employed for treatment, the emergence of drug resistance significantly influences survival and prognosis." (PMID 41154659, 2025). "Other enzymes, such as PGI, PGK-1 and ENO-2, were found to be downregulated in an epidermal growth factor receptor (EGFR)-mutant non-small-cell lung cancer (NSCLC) with advanced resistance to EGFR tyrosine kinase inhibitors (TKIs), such as erlotinib." (PMID 39904372, 2025). "In this study, we demonstrated that FTO played an important role in tumor proliferation and cell migration, as well as mediating EGFR TKI resistance in non-small cell lung cancer." (PMID 40722726, 2025). "Osimertinib has been the standard treatment for advanced Epidermal Growth Factor Receptor (EGFR)-driven non-small cell lung cancer (NSCLC) for many years." (PMID 40075694, 2025). "Our case illustrates that 160 mg of osimertinib administered concurrently with a strong CYP3A4 inducer can be given safely and with retained efficacy in treating CNS metastatic EGFR-positive non-small cell lung cancer." (PMID 40256355, 2025). "A 35-year-old man with metastatic non-small cell lung cancer harboring a deletion in exon 19 of epidermal growth factor receptor developed acute right ventricular failure and hemodynamic collapse due to pulmonary tumor thrombotic microangiopathy." (PMID 41348429, 2025).
non-small cell lung carcinoma (continued). "RTKi revolutionised the treatment of BCR-ABL1-positive chronic myeloid leukaemia, human epidermal growth factor receptor 2 (HER2)-positive breast cancer, and epidermal growth factor receptor (EGFR)-mutant non-small cell lung cancer (NSCLC)." (PMID 41511287, 2025). "Our case provides evidence that osimertinib 160 mg can be safely administered concurrently with a known CYP3A4 inducer while preserving efficacy in CNS metastatic EGFR positive non-small cell lung cancer." (PMID 40256355, 2025). "A study showed that lupeol therapy inhibited colony formation, cell proliferation, and EGFR phosphorylation in NSCLC (Non-small cell lung cancer) cells." (PMID 40417209, 2025). "These values were comparable to those of the reference inhibitor Erlotinib, an FDA-approved EGFR-targeting drug used in non-small cell lung carcinoma (-9.0 3 kcal/mol), indicating promising inhibitory potential." (PMID 41455835, 2025). "For instance, in copy number omics, we discover pathways corresponding to genes like EGFR, CDK6, RASSF5, BRAF, and CCND1, which are associated with non-small cell lung cancer." (PMID 40191608, 2025). "Osimertinib, a third-generation epidermal growth factor receptor (EGFR) tyrosine kinase inhibitor (EGFR-TKI), has become a first-line treatment for non-small cell lung cancer (NSCLC) with EGFR mutations." (PMID 40156608, 2025). "Epidermal growth factor receptor (EGFR) mutations occur in approximately 10–20% of Caucasian and up to 50% of Asian patients with oncogene-addicted non-small cell lung cancer (NSCLC)." (PMID 40725428, 2025). "Her hospital course was further complicated by a diagnosis of metastatic non-small cell lung cancer harboring an epidermal growth factor receptor exon 19 deletion." (PMID 41216073, 2025). "IKBKE overexpression is linked to chemotherapy resistance, particularly to cisplatin and paclitaxel in breast and ovarian cancers, as well as resistance to EGFR tyrosine kinase inhibitors in non-small cell lung cancer." (PMID 41378297, 2025). "Some studies hint towards the impact of EGFR inhibition on the induction of CIITA expression in non-small cell lung cancer; however, studies are warranted that will validate these findings in CRC and to exploit them for better patient treatment." (PMID 40141198, 2025). "EGFR tyrosine kinase inhibitors (TKIs) have proven to be effective in non-small-cell lung cancer (NSCLC), where they are the major first-line therapy for patients with activating EGFR mutations." (PMID 40332381, 2025). "EGFR is a well-characterised oncogenic receptor tyrosine kinase in non-small cell lung cancer, colon cancer and several other malignancies." (PMID 41271784, 2025). "Another study demonstrated that metastatic sites were similar between EGFR-mutant and wild-type non-small cell lung cancer types." (PMID 40004680, 2025). "The present retrospective study was thereby conducted to investigated the efficacy and safety of the BRICS sequential therapeutic regimen in PD-L1-negative metastatic non-small cell lung cancer patients harboring EGFR/ALK wild-type status." (PMID 40625736, 2025). "The co-occurrence of epidermal growth-factor receptor (EGFR) mutation and de novo or acquired MET exon 14 skipping (METex14) mutation in non-small-cell lung cancer (NSCLC) is extraordinarily rare." (PMID 41316444, 2025). "The T790M mutation is a significant mechanism of acquired resistance to EGFR-TKIs in non-small cell lung cancer (NSCLC)." (PMID 41234359, 2025). "L-1 that shows the highest biological activity across BaF3 cell, mutant EGFR kinase and LSD1 assays due to its dual targeting of LSD1/EGFR, emerges as a promising lead compound for non-small cell lung cancer treatment." (PMID 39753983, 2025). "While EGFR tyrosine kinase inhibitors (TKIs) have transformed the management of EGFR-mutant non-small cell lung cancer, their role in other malignancies remains under investigation." (PMID 40364160, 2025).